TCEAL6 (transcription elongation factor A like 6)
Description:
May be involved in transcriptional regulation.
Synonyms: WEX2
Tractability: No criterion of Open Targets' tractability assessment is met for any kind of drug.
Gene: Protein-coding gene on chromosome X (102,140,476 to 102,142,970, reverse strand). Ensembl gene ENSG00000204071.
Subcellular location: Nucleus
Subcellular location (Human Protein Atlas): Nucleoplasm
Gene Ontology:
Cellular component: nucleus
Homologues: Orthologues: macaque TCEAL6 (94% identical), dog TCEAL3 (82% identical), dog TCEAL6 (80% identical), mouse Tceal6 (73% identical), mouse Tceal3 (72% identical), rat Tceal3 (71% identical), rat Tceal6 (71% identical), mouse Tceal5 (68% identical), rat Tceal5 (66% identical). Paralogues in human: TCEAL3 (96% identical), TCEAL5 (89% identical), TCEAL4 (49% identical), TCEAL2 (47% identical), TCEAL8 (20% identical), TCEAL1 (17% identical), TCEAL9 (16% identical), TCEAL7 (16% identical).
Diseases named in the same sentence as TCEAL6 in open-access papers:
TCEAL6 is named in the same sentence as 1 disease in open-access papers, as found by Europe PMC text mining. Sharing a sentence is not in itself a finding about the gene and the disease.
TCEAL6 shares sentences with these, for which no sentence is quoted: cervical cancer (1 paper).